SMARCB1 (SWI/SNF related BAF chromatin remodeling complex subunit B1)
Diseases named in the same sentence as SMARCB1 in open-access papers (continued):
Sharing a sentence is not in itself a finding about the gene and the disease.
sinonasal carcinoma (continued). "We report a case of SMARCB1-deficient sinonasal carcinoma with clear cell morphology." (PMID 38836164, 2024). "Based on these findings, a diagnosis of SMARCB1-deficient sinonasal carcinoma was made." (PMID 38836164, 2024). "SMARCB1-deficient sinonasal carcinoma is prone to recurrence and has a very poor prognosis." (PMID 38836164, 2024). "EZH2 inhibitors are promising therapeutic candidates for SMARCB1-deficient sinonasal carcinoma." (PMID 38836164, 2024). "Currently, less than 200 cases of SMARCB1-deficient sinonasal carcinoma have been reported." (PMID 38836164, 2024). "We encountered a case of SMARCB1-deficient sinonasal carcinoma with clear cell morphology." (PMID 38836164, 2024). "The differential diagnosis is broad and should include adenoid cystic carcinoma, basaloid squamous cell carcinoma, adenosquamous carcinoma, high-grade myoepithelial carcinoma, biphenotypic sinonasal sarcoma, NUT carcinoma, SMARCB1-deficient sinonasal carcinoma, and renal cell-like adenocarcinoma." (PMID 39319059, 2024). "A total of 17 patients died of SMARCB1-deficient sinonasal carcinoma." (PMID 39398818, 2024). "SMARCB1-deficient sinonasal carcinomas predominantly exhibit a basaloid (~ 2/3) or rhabdoid (~ 1/3) morphology; the latter may be very focal." (PMID 36941503, 2023). "SMARCB1 (INI-1)-deficient sinonasal carcinoma is a rare but locally aggressive malignancy which usually presents very late with invasion into the orbits and intracranium, and compression of adjacent cranial nerves and their branches at diagnosis, and has a poor survival outcome." (PMID 35805058, 2022). "So far, only less than 200 patients with SMARCB1-deficient sinonasal carcinoma have been reported." (PMID 35805058, 2022). "Like SWI/SNF-deficient neoplasms in different organs, SMARCB1-deficient sinonasal carcinoma may show focal immunoreactivity for different neuroendocrine markers." (PMID 35307773, 2022). "Retrospective studies on using proton therapy and carbon ion therapy for sinonasal carcinoma including a patient with SMARCB1-deficient sinonasal carcinoma could achieve a local and regional control rate of about 85%, with very limited grade 3 or 4 toxicities." (PMID 35805058, 2022). "Of them, tumor progression of SMARCB1-deficient sinonasal carcinoma was the most common cause of death (44 patients, 77.2%), followed by unknown causes (7 patients, 12.3%), and cerebrovascular events (6 patients, 10.5%)." (PMID 35805058, 2022). "Quite often, SMARCB1-deficient sinonasal carcinoma presents as small blue round cell tumors which mimic other sinonasal malignancies including undifferentiated carcinoma, NUT sinonasal carcinoma, lymphoma, small cell carcinoma, olfactory neuroblastoma, melanoma, and rhabdomyosarcoma." (PMID 35805058, 2022). "Loss of SMARCB1 because of biallelic inactivation of its gene in a subset of poorly or undifferentiated sinonasal carcinoma has been first described in 2014 by two independent groups, followed by a few additional series including one large multi-institutional series (n=39)." (PMID 35307773, 2022). "On the other hand, small-cell SNECs and SMARCB1-deficient sinonasal carcinomas seem to be molecularly distinct from IDH2-mutated carcinomas, as supported by the distribution of ARID1A mutations, which were common in small-cell SNEC but not among IDH2-mutant cancers." (PMID 35059992, 2022). "Rare myoepithelial carcinomas with rhabdoid features may display SMARCB1 loss and, when presenting in the sinonasal tact, may mimic SMARCB1-deficient sinonasal carcinomas." (PMID 35307773, 2022). "However, very limited data is available on its efficacy against SMARCB1-deficient sinonasal carcinoma." (PMID 35805058, 2022). "Notably, this group of high-grade carcinomas presented a better disease-free survival and lower propensity for lung metastasis than SMARCB1 deficient sinonasal carcinomas." (PMID 35326613, 2022).
sinonasal carcinoma (continued). "To date, SMARCB1 loss has been described in about 100 sinonasal carcinomas worldwide, mostly among SNUC, and a worse outcome has been demonstrated in these cases, while more rarely, this alteration was observed in NKSCC and in tumors with plasmacytoid and rhabdoid morphologies." (PMID 34638515, 2021). "Additionally, recently described entities include INI (SMARCB1)-deficient sinonasal carcinoma and NUT carcinoma." (PMID 34285947, 2021). "Among these new tumor variants, such as NUT-rearranged carcinoma, HPV-related adenoid cystic-like carcinoma, and adamantinoma-like Ewing sarcoma, SMARCB1-deficient sinonasal carcinoma (SDSC) stands out given its aggressiveness in the face of multimodal therapy." (PMID 31438887, 2019). "Thus, there is a clinicopathological similarity between the present case and SMARCB1-deficient sinonasal carcinoma." (PMID 29625594, 2018). "Whether our case could be understood as a thoracic counterpart of SMARCB1-deficient sinonasal carcinoma remains to be seen based on future studies of a large number of cases." (PMID 29625594, 2018). "The insignificant difference in SMARCB1 expression in lung patients is consistent with previous studies that indicated that SMARCB1 mutation was frequently observed in pancreatic cancer, gastrointestinal cancer, and sinonasal carcinoma, but it was seldom recorded in lung carcinoma." (PMID 39313797, 2024). "Therefore, it is advisable to perform a molecular genetic search in addition to an immunohistochemical search to determine whether the lesion is a typical SMARCB1-deficient sinonasal carcinoma wherein both searches are abnormal." (PMID 38836164, 2024). "However, SMARCB1-deficient sinonasal carcinoma is highly invasive and has a very poor prognosis." (PMID 38836164, 2024). "SMARCB1-deficient and SMARCA4-deficient sinonasal carcinomas are rare, with only a few systematic studies available in the literature." (PMID 40366517, 2025). "Among the subunits that have been studied extensively (SMARCB1, SMARCA4, SMARCA2, and ARID1A), the loss of SMARCB1 and SMARCA4 has been implicated in sinonasal carcinomas." (PMID 40366517, 2025). "A complete loss of SMARCB1 (testing INI1]) and SMARCA4 (testing BRG1) reactivity in the tumor nuclei is essential for the diagnosis of SMARCB1-deficient and SMARCA4-deficient sinonasal carcinoma, respectively." (PMID 36941503, 2023). "Contrasting with their SMARCB1-deficient counterparts, the basaloid small cell pattern is much infrequent in SMARCA4-deficient sinonasal carcinomas." (PMID 35307773, 2022). "DNA methylation profiling of olfactory neuroblastomas and a cohort of sinonasal carcinomas showed that IDH2 mutated and SMARCB1 deficient carcinomas likely represent epigenetically distinct classes." (PMID 36443295, 2022). "SMARCB1 copy number analysis was possible in 41 out of 53 sinonasal carcinomas with a good quality DNA, including 8 INI1-negative cases and 33 cases with a normal expression of INI1 protein." (PMID 34638515, 2021). "One interesting analogy to our case is with the recently characterized SMARCB1-deificnet sinonasal carcinomas." (PMID 29625594, 2018). "Loss of the entire chromosome 22q has been reported in other human tumors but has not yet been documented in SMARCB1-deficient sinonasal carcinomas." (PMID 40366517, 2025). "Of the 149 sinonasal carcinomas, 7 (4.7%) showed SMARCB1 loss, while none demonstrated SMARCA4 loss." (PMID 40366517, 2025). "In fact, a definitive diagnosis of SMARCB1-deficient sinonasal carcinoma was not established in the initial biopsy specimens from two cases (Cases 2 and 6); an accurate diagnosis was rendered in the resection specimens." (PMID 40366517, 2025). "Conservation of INI-1 ruled out SMARCB1-deficient sinonasal carcinoma and negativity for NUT rules out NUT carcinoma." (PMID 39319059, 2024).
sinonasal carcinoma (continued). "Sinonasal carcinomas characterized by rhabdoid/basaloid morphology and loss of expression of the SWI/SNF complex (SMARCB1, SMARCA4, SMARCA2), previously viewed as a subset of SNUCs, are recognized as a standalone entity in the 5th edition WHO Classification of Head and Neck Tumours." (PMID 38315310, 2024). "There are four different subtypes of SWI/SNF complex deficient sinonasal/base of skull malignancies, including SMARCB1-deficient sinonasal carcinoma, SMARCB1-deficient sinonasal adenocarcinoma, SMARCA4-deficient sinonasal carcinoma, and a subset of SMARCA4-deficient teratocarcinosarcomas." (PMID 38491228, 2024). "Reports indicate that SMARCB1 deficits are found in 2.7% to 6% of sinonasal carcinomas." (PMID 39398818, 2024). "It is now called SMARCB1-deficient sinonasal carcinoma or switch/sucrose nonfermenting (SWI/SNF) complex-deficient sinonasal carcinoma." (PMID 38836164, 2024). "SMARCB1-deficient sinonasal carcinoma is defined by a lack of features of any other defined sinonasal carcinoma type, complete loss of SMARCB1 expression, and absence of morphologic squamous or glandular differentiation." (PMID 38491228, 2024). "Here, we have presented the largest systematic review of patient characteristics, treatment details, and survival outcomes of patients with SMARCB1-deficient sinonasal carcinoma, among the two previously published which did not include all reported cases." (PMID 35805058, 2022). "A higher predilection for males (5:1) is observed compared to non-glandular SMARCB1-deficient sinonasal carcinomas." (PMID 35307773, 2022). "To date, no standard treatment for SMARCB1-deficient sinonasal carcinoma has been established." (PMID 38836164, 2024). "These two cases, wherein FISH detected no EWSR1 and SMARCB1 gene abnormalities, might represent a different tumor type from SMARCB1-deficient sinonasal carcinoma." (PMID 38836164, 2024). "The loss of SMARCB1 (INI1) protein expression, which is a member of the chromatin-remodeling SWI/SNF complex located at 22q11.2, can be identified in selected cases of poorly or undifferentiated sinonasal epithelial cancers, referred to as SMARCB1-deficient sinonasal carcinomas." (PMID 35059992, 2022). "Among the 149 sinonasal carcinomas analyzed, SMARCB1 (INI1) expression was lost in 7 tumors (4.7%) (95% confidence interval: 1.7–10.3%), while none showed loss of SMARCA4 (BRG1) expression by immunohistochemical staining (0/149) (95% confidence interval: 0 to 4.6%)." (PMID 40366517, 2025). "A second group of molecularly defined undifferentiated sinonasal carcinomas presents loss of one SWI/SNF (SWItch/Sucrose Nonfermentable) chromatin remodeling complex subunit, usually either SMARCB1 or SMARCA4." (PMID 35326613, 2022).
Coffin-Siris syndrome (36 papers, 2012 to 2026). "We performed cellular, molecular, and behavioural analyses of a Coffin-Siris syndrome mouse model with a heterozygous nervous system-specific Smarcb1 mutation." (PMID 41715173, 2026). "Comparable cognitive and behavioural deviations were identified in individuals with Coffin-Siris syndrome and SMARCB1 pathogenic variants." (PMID 41715173, 2026). "Germline PVs in SMARCB1 cause the clinically and genetically heterogeneous Coffin-Siris syndrome (CSS, MIM #135900)." (PMID 40794298, 2025). "Case 1008: a rare heterozygous variant in the SMARCB1 gene (NM_003073.3) c.364del (p.Glu122Asnfs*21) was previously identified in an individual clinically diagnosed with Coffin-Siris syndrome." (PMID 40593860, 2025). "PVs in the highly basic SMARCB1 C-terminal alpha-helical region cause Coffin-Siris syndrome, a neurodevelopmental disorder associated with severe intellectual disability (Sect." (PMID 40794298, 2025). "Here, we present two prenatal Coffin-Siris syndrome cases with autosomal dominant pathogenic variants: SMARCB1 gene c.1066_1067del, p.(Leu356AspfsTer4) variant, and a novel ARID1A gene c.1920+3_1920+6del variant." (PMID 37981638, 2024). "Coffin-Siris syndrome is caused by pathogenic variants in 12 different genes including SMARCB1 and ARID1A." (PMID 37981638, 2024). "This combination has actually been described very recently for a related gene causing Coffin-Siris syndrome, the SMARCB1 gene." (PMID 26803492, 2016). "Later published studies discovered the etiology of the phenotypically related Coffin-Siris syndrome to be caused by similar mutations in SMARCB1 and ARID1B, which are direct interaction partners of SMARCA2 in the SWI/SNF chromatin remodeling complex." (PMID 23013645, 2012). "In addition, SMARCB1 is mutated in intellectual disability disorders such as Coffin–Siris syndrome and Kleefstra’s syndrome, indicating alterations of SMARCB1 have devastating pathological outcomes in many contexts." (PMID 39542244, 2024). "The relationship between reduced or dysfunctional SMARCB1 protein products and severe functional brain changes associated with Coffin-Siris syndrome, including intellectual disability and severely delayed language and motor development, remains largely unknown." (PMID 41715173, 2026). "Coffin–Siris syndrome is also called “BAFopathy” because its causal genes encode chromatin modeling BAF complex components (e.g., ARID1B and SMARCB1)." (PMID 38094004, 2023). "There was also a known pathogenic variant in SMARCB1 in a fifth atypical case, where AIC was only suspected, that provided an alternate diagnosis of Coffin–Siris syndrome." (PMID 37628618, 2023). "The current EpiSignTM BAFopathy episignature encompasses several subtypes of Coffin–Siris syndrome associated with multiple genes (ARID1A, ARID1B, SMARCB1, SMARCA4) and Nicolaides–Baraitser syndrome (SMARCA2)." (PMID 36430143, 2022). "Lastly, a mouse model for Arid1b and Smarcb1 deficits (Coffin-Siris Syndrome) indeed mirror the human phenotype, as Arid1b+/− and Smarcb1+/inv NesCre+/− mice also have a significantly reduced corpus callosum thickness." (PMID 33263776, 2021). "In this study, authors establish the first Smarcb1 mutant mouse model with multiple brain abnormalities recapitulating human Coffin–Siris syndrome and show that one prominent midline abnormality, corpus callosum agenesis, is due to midline glia aberrations." (PMID 31273213, 2019). "In addition, we evaluated general cognitive abilities, as well as cognitive and behavioural functioning, in individuals with SMARCB1-related Coffin-Siris syndrome." (PMID 41715173, 2026). "SMARCB1 encodes a core component of the BAF chromatin remodelling complex and pathogenic variants in this gene are associated with neurodevelopmental disorders such as Coffin-Siris syndrome and intellectual disability with choroid plexus hyperplasia." (PMID 41715173, 2026).
Coffin-Siris syndrome (continued). "Exons 8 and 9 of SMARCB1 fully encode the C-terminal coiled-coil domain (CTD), which harbors recurrently observed missense mutations in cancers and the rare developmental disorder Coffin-Siris syndrome." (PMID 40120586, 2025). "Interestingly, germline variants of SMARCB1 and SMARCA4 have been identified also in patients with Coffin-Siris syndrome three (CSS3, OMIM #614608) and four (CSS4, OMIM #614609)." (PMID 33692948, 2021). "Two patients had germline splice variants of SMARCB1, though neither exhibited clinical phenotype of the associated Coffin-Siris syndrome." (PMID 34722256, 2021). "For instance, the SMARCB1, SMARCA4, SMARCE1, ARID1A, and ARID1B genes encode subunits of the BAF complex (also known as the SWI/SNF complex in yeast), and they are responsible for 55–70% of Coffin–Siris syndrome cases, where microcephaly can manifest as one of the phenotypes." (PMID 38094004, 2023). "Germline mutations in SMARCA4, SMARCB1, and other SWI/SNF components also cause Coffin-Siris syndrome (CSS), a developmental disorder primarily characterized by developmental delay and intellectual and physical disabilities." (PMID 27866340, 2017). "First described in 1970, Coffin–Siris syndrome is an intellectual disability disorder that is caused by mutations in genes encoding individual subunits of the BAF (BRG1/BRM-associated factor) complex, including ARID1A, ARID1B, SMARCA2, SMARCA4 (BRG1), SMARCB1 (INI1), and SMARCE1 (BAF57)." (PMID 26103525, 2015). "In contrast to other genetic disorders related to PVs in SMARCB1 and SMARCA4 such as Coffin-Siris Syndrome, RTPS1&2 are characterized by a predominance of truncating PVs, terminating transcription thus explaining a specific cancer risk." (PMID 33532948, 2021). "Mutations in other genes involved with the SWI/SNF complex such as ARID1A, SMARCA2, SMARCA4, SMARCB1 and SMARCE1 are also responsible for Coffin-Siris syndrome." (PMID 26376624, 2015). "In both cases, early alterations in Smarcb1 function (rather than in the mature brain) are most likely to initiate disease development as, e.g., children with Coffin-Siris Syndrome are symptomatic at birth and AT/RT exclusively develop in early childhood." (PMID 35456033, 2022). "Coffin-Siris syndrome is a developmental disorder leading to intellectual disability, distinctive facial features and hypoplastic fingers and toes—features that are not seen in RTPS1 or SMARCB1-SWN." (PMID 41284083, 2025). "In case of SMARCB1 both the type (truncating versus non-truncating missense) and location in the gene determine the phenotype (low-grade malignancies, malignant rhabdoid tumors, Coffin-Siris syndrome)." (PMID 35856126, 2023). "Sequence variants in other BAF complex genes are associated with other neurodevelopmental disorders including SMARCC1/2, PBRM1, ARID1A/B and SMARCA4 in ASD, PBRM1 and ARID1B in schizophrenia, SMARCB1 in Kleefstra syndrome, and ARID1A/B, SMARCA4, SMARCB1, and SMARCE1 Coffin-Siris syndrome (CSS)." (PMID 31288860, 2019).